ARK2N (arkadia (RNF111) N-terminal like PKA signaling regulator 2N)
Description:
AMPK substrate important for exercise capacity and skeletal muscle function. Required for normal contraction-induced signaling. (Microbial infection) Upon Epstein-Barr virus (EBV) infection, suppresses viral BZLF1 expression and subsequent EBV reactivation by interacting with JUN and inhibiting its transcriptional activator activity on BZLF1 Z promoter.
Synonyms: ARKL1; C18orf25; MGC12909; RNF111L1
Tractability: PROTAC: UniProt records ubiquitination sites on it; ubiquitination databases record sites on it.
Gene: Protein-coding gene on chromosome 18 (46,173,508 to 46,266,992, forward strand). Ensembl gene ENSG00000152242.
Subcellular location: Nucleus
Subcellular location (Human Protein Atlas): Nucleoplasm; Cytosol
Gene Ontology:
Molecular function: protein binding; transcription corepressor activity; ubiquitin protein ligase activity
Biological process: negative regulation of viral life cycle; ubiquitin-dependent protein catabolic process; negative regulation of DNA-templated transcription
Cellular component: chromatin; nucleus
Genetic constraint (gnomAD): Loss-of-function variants: 16 observed, 36.39 expected, observed/expected ratio (o/e) 0.44, 90% interval 0.3 to 0.67. The upper end of that interval is the gene's LOEUF score, 0.67, which puts it in group 2 of 6, group 1 being the genes least tolerant of losing a copy. Missense variants: 430 observed, 513.2 expected, observed/expected ratio (o/e) 0.84, 90% interval 0.77 to 0.91. Synonymous variants: 168 observed, 196.46 expected, observed/expected ratio (o/e) 0.86, 90% interval 0.75 to 0.97.
Homologues: Orthologues: chimpanzee ARK2N (100% identical), macaque ARK2N (99% identical), pig ARK2N (98% identical), dog ARK2N (97% identical), mouse Ark2n (94% identical), rat Ark2n (93% identical), rabbit ARK2N (75% identical), tropical clawed frog ark2n (74% identical), zebrafish ark2n (40% identical), Drosophila melanogaster CG6923 (28% identical), Caenorhabditis elegans toe-4 (9% identical). Paralogues in human: RNF111 (26% identical), ARK2C (7% identical).
Diseases named in the same sentence as ARK2N in open-access papers:
ARK2N is named in the same sentence as 6 diseases in open-access papers, as found by Europe PMC text mining. Sharing a sentence is not in itself a finding about the gene and the disease. The quoted sentences say what the papers report.
muscle degeneration (1 paper, 2024). "Targeting ARK2N could pave the way for novel therapeutic strategies to preserve or enhance muscle function in aging populations and individuals at risk of muscle degeneration." (PMID 39728465, 2024).
sarcopenia (1 paper, 2024). Progressive decline in muscle mass due to aging which results in decreased functional capacity of muscles. "Future research should focus on elucidating the molecular mechanisms of ARK2N in muscle adaptation, validating its effects across diverse populations, and investigating its potential as a therapeutic target for sarcopenia and other muscle-related conditions." (PMID 39728465, 2024).
ARK2N also shares sentences with these, for which no sentence is quoted: infection (2 papers); melanoma (1); prostate carcinoma (1); tumor (1).